GLI1 (GLI family zinc finger 1)
Diseases named in the same sentence as GLI1 in open-access papers (continued):
Sharing a sentence is not in itself a finding about the gene and the disease.
cancer (continued). "REG4 transcription is induced by the GLI1 transcription factor, which is activated by sonic hedgehog, regulates stem cell proliferation, and is associated with a poor cancer prognosis." (PMID 24533081, 2014). "The prevalent hedgehog-related therapeutic strategy assessed so far is the inhibition of the Smo/Gli-1 canonical pathway, which is believed to be activated in some cancers because of Ptc/Smo mutation(s)." (PMID 23940460, 2013). "Several types of human cancers have demonstrated aberrant activation of the HH pathway by ligand-independent signaling such as, amplification of GLI1 or GLI2, mutations in PTCH or SMO, or dysregulated gene expression." (PMID 21860067, 2011). "Hh-ligand-independent activation of GLI1 expression via loss of PTCH or oncogenic mutations in SMO have been reported for a number of cancers and pharmacological inhibition with SMO-directed inhibitors shown to block Hh signalling and cell proliferation." (PMID 21505458, 2011). "In light of these new insights, this review will provide a comprehensive overview on GLI1 polymorphisms and the three members of the GLI1 family of proteins, and their impacts on human diseases, including, cancers." (PMID 21119888, 2010). "Mechanistically, GPR137 enhances stabilization of RAB8A mRNA and the up-regulated RAB8A expression activates HH signaling by destroying the SuFu-GLI1 complex, leading to the release of GLI1 and thereby its translocation into the nucleus to trans-activates cancer-associated target genes." (PMID 39856733, 2025). "Importantly, we found that GLI1/2/3 modulated the immune microenvironment by regulating the recruitment, activation, and polarization of cancer-associated fibroblasts, endothelial cells, and macrophages." (PMID 38498906, 2024). "Additionally, unlike HIF1α or EZH2, GLI-1 was the sole transcription factor activated by integrin-linked focal adhesion kinase, indicating GLI-1 as a key driver of the EZH2-integrin α11 axis operating for cancer stem cell survival and EMT." (PMID 38664825, 2024). "GLI1 expression has been associated with a poor prognosis and an advanced stage of various cancers." (PMID 38999049, 2024). "Finally, we performed enrichment analysis to decipher the underlying mechanisms of GLI1/2/3 in cancer initiation and progression." (PMID 38498906, 2024). "Furthermore, GLI1/2/3 expression displayed significant associations with poor prognosis in several cancers, indicating their potential as prognostic biomarkers and therapeutic targets." (PMID 38498906, 2024). "Additionally, the Hh pathway in TNBC promotes stem cell populations, activates cancer‐associated fibroblasts, enhances cancer cell invasiveness, and facilitates angiogenesis through the upregulation of GLI1/2 transcription." (PMID 39558881, 2024). "Taken together, the ProstaMine results and results from other cancer types suggest that targeted inhibition of GLI1 or the SHH-GLI1 pathway may reduce the aggressiveness of NKX3-1-loss and RB1-loss PCa." (PMID 38751776, 2024). "Disruption of the Shh–GLI1 pathway has been consistently associated with tumorigenesis and the emergence of aggressive phenotypes, including disease progression, metastasis, and resistance to therapy, in various cancer types." (PMID 37894854, 2023). "In previous studies, GLI1 signal transduction and other pathways, including the NF-κB signaling pathway, were usually studied in tumor-associated diseases and are considered a response network that promotes cancer development." (PMID 37929702, 2023). "Interaction between the MAPK pathway and GLI1 protein of the SHH pathway has been implicated in cancer progression in multiple cancers, and targeting a combination of these pathways could serve as another tool to decipher drug resistance to SHH inhibitors." (PMID 35327484, 2022). "Constitutive activation of GLI1 is associated with several types of cancer." (PMID 33958721, 2021). "Expression of GLI1 is associated with a poor prognosis in a wide variety of cancers." (PMID 34639011, 2021).
cancer (continued). "Interestingly, canonical HH signaling or ectopic expression of GLI1 causes genomic instability and cancer predisposition by faulting the S-phase checkpoint, DNA repair mechanisms, and inhibiting DNA double-strand breaks (DSBs)-mediated DDR." (PMID 33494284, 2021). "GLI1 has low-level expression in differentiated tissues, however, in certain cancers, aberrant activation of GLI1 has been linked to the promotion of numerous hallmarks of cancer, such as proliferation, survival, angiogenesis, metastasis, metabolic rewiring, and chemotherapeutic resistance." (PMID 34113570, 2021). "Notably, loss of SNF5, observed in malignant rhabdoid tumors, has been associated with derepression of transcriptional activity at GLI1 locus and hyperactivation of HH signaling, which contributes to cancer formation." (PMID 31244888, 2019). "Pathogenic Hh pathway activation may occur in cancer at several levels of the Hh signal transduction cascade, including mutations in Ptch1, Smo, and Sufu, as well as amplification of Gli1." (PMID 31137846, 2019). "GLI1 is a human oncogene and constitutive activation, either as a result of canonical pathway activation or non-canonical activation, of GLI1 is associated with many human cancers." (PMID 31085420, 2019). "Furthermore, Rab1A was associated with S6K levels in 7 cancers, with Gli1 in 2 cancers, AKT in 7 cancers, HER2 in 2 cancers, and with EGFR in 6 cancers." (PMID 31527621, 2019). "Activation of Hh signaling in cancer can occur via several mechanisms, such as ectopic production of Hh ligands, somatic mutations in the Hh pathway components, Ptch1, Smo, Sufu, and/or amplifications of the Hh transcription factor Gli1." (PMID 31137846, 2019). "Somatic or germline mutations of GLI1 have been reported in several cancers." (PMID 26633513, 2015). "These GLI1 target genes highlight a pivotal role of GLI1 in cancer biology, but whether and how GLI1 is linked to the metastasis of cancer is yet to be fully understood." (PMID 26413813, 2015). "Among these, GLI1 (glioma-associated oncogene 1) encodes a transcription factor that is a marker of Hedgehog signaling activation, and its increased expression is associated with a wide variety of human cancers." (PMID 25654223, 2015). "The (GLI1ΔN) variant acts on genes similarly to GLI1 in both normal and cancer cells." (PMID 26633513, 2015). "In addition, the expression of sonic hedgehog (Shh) and glioma-associated oncogene homolog zinc finger protein 1 (Gli1) has been shown to affect lymphatic metastasis in cancer." (PMID 25141859, 2014). "GLI1 is amplified in glioblastoma and has been implicated in other cancers." (PMID 25252859, 2014). "Gli1 activity is generally associated with disease progression in cancer." (PMID 23900341, 2013). "Since Hh signaling has been linked to a variety of cancers, some of which develop in the setting of inflammation, we examined the role of Gli1, a known component of the Hh signaling pathway, in the transition from chronic inflammation to mucous neck cell metaplasia or SPEM." (PMID 23520544, 2013). "Conversely, GLI1 knockdown led to a decrease in these cancer-associated phenotypes in HCC cells." (PMID 23185371, 2012). "It will be also of importance to further explore the frequency of GLI1 codon 1100 polymorphism in other human diseases, such as cancers, given the interesting fact that the GLI1 E1100 variant is carried by the two GBM cell lines (D-259 MG and U87MG) that have been genotyped thus far." (PMID 21119888, 2010). "The zinc finger protein glioma-associated oncogene homologue 1 (Gli-1) is a critical component of the Hedgehog (Hh) signalling pathway, which is essential for morphogenesis and stem-cell renewal, and is dysregulated in many cancer types." (PMID 18475300, 2008).
cancer (continued). "Moreover, the HH-GLI pathway has been associated with cancer stem cell properties, and the crosstalk between the NFκ-B and GLI1 pathways highlights the importance of GLI1 in promoting cell dedifferentiation and stemness derived from the activation of the PI3K/Akt/NFK-β signaling pathway." (PMID 38473317, 2024). "However, aberrant HH signaling due to truncated GLI1 can cause several human cancers." (PMID 36836780, 2023). "As previously stated, GLI1 induced by Hh signaling is important in the regulation of cellular proliferation, stemness, cell fate determination, and cellular survival in a variety of organs; however, its aberrant activation has been associated with many human cancers." (PMID 34113570, 2021). "Therefore, understanding the role of SHH dysregulation in SHH-mediated cancers and how the novel GLI1 splice variants may promote various phenotypes is paramount to further mechanistic discovery and drug development." (PMID 32957513, 2020). "Furthermore, overexpression of GLI1 is often associated with the metastasis ability of cancers." (PMID 29190924, 2017). "GLI1 is a key transcription factor in the HH signaling pathway, which is known to be aberrantly activated in various cancers, including GBM." (PMID 41596413, 2026). "Both were reported to inhibit Gli-mediated gene activation, but GANT61 proved more potent inhibition on Gli1 and Gli2 in many cancer cell lines." (PMID 40651614, 2025). "Previous studies have indicated that small molecule drugs can directly bind to Gli1 within the stemness pathway and suppress its expression, thereby inhibiting stemness and exerting anti-cancer effects." (PMID 41451369, 2025). "The underlying mechanism demonstrated that GLI1 directly controls NBS1 expression, and blocking GLI1 effectively resulted in reducing NBS1 levels and therefore increasing cancer cells’ vulnerability to damage and death." (PMID 39851545, 2025). "This proposes new strategies for implementing hyperthermia to target GLI1 driven cancers to improve therapeutic efficacy." (PMID 41497797, 2025). "In summary, our data indicated that CSNK1D promoted HNSCC cancer progression by increasing the nucleus entry of GLI1 and activating the hedgehog GLI1/BCL2 signaling pathway." (PMID 41353440, 2025). "Target GLI1 is a powerful cancer therapy strategy and many agents that target GLI1 are on preclinical trials stage." (PMID 41497797, 2025). "Since spheres formation assay is a tool to detect stemness of cancer cells, our data revealed that spheres number and size both significantly decreased in GLI1 knockdown group." (PMID 41497797, 2025). "When activated by SMO or other signaling, GLI1 can be translocated into nucleus and orchestrate expression of its downstream oncogenes, leading to cancer development and progression." (PMID 41323789, 2025). "As the downstream transcriptional factor of the Hh pathway, GLI1 plays a crucial role in cancer progression and prognosis evaluation, while it is activated by an SMO-dependent or independent manner." (PMID 41323789, 2025). "Curcumin also inhibits the nuclear translocation of GLI1, a critical step for its transcriptional activity and role in cancer cell proliferation." (PMID 40227413, 2025). "Within this family of transcription factors, Gli1 and Gli2 constitute key transcription effectors with regard to tumorigenesis, and constitutive activation of at least one of them is essential for cancer development." (PMID 40651614, 2025). "According to the literatures that respectively launched by Wang K 34, Sun Y 35 and Sun J 36, GLI1 inhibition arrested cell cycle at G0/G1 or G2/M phase in cancers of brain, cartilage, and esophagus." (PMID 41323789, 2025). "Data from reporterassays and expression analysis consistently indicated inhibition ofendogenous Gli1 protein levels as well as proteins that promote cellproliferation and survival in A549 and DU-145 cancer cells." (PMID 40124057, 2025).
cancer (continued). "Previous studies have shown that the SHH pathway, particularly GLI1, influences tumorigenesis in both cancer cells and cancer stem cells." (PMID 40894044, 2025). "This interaction is facilitated by the regulation of Gli1’s nuclear localization and transcriptional activity, which is crucial for cancer development." (PMID 39900571, 2025). "Similar to GLI1 knockdown, ESCC cells treated with hyperthermia showed growth inhibition associated with the downregulation of cancer stemness proteins." (PMID 41497797, 2025). "A series of studies prove that GLI1 inhibition induced cell cycle arrest in different cancer types 22-24." (PMID 41323789, 2025). "While in many types of cancers, the activated hedgehog signaling is independent on primary cilia, as cancer cells lose primary cilia and upregulated GLI1 level directly, the detail mechanism is still poorly understood." (PMID 41497797, 2025). "GLI1 is the key downstream molecular of hedgehog signaling, which is a transcription factor and regulates cancer cell stemness, proliferation, metastasis, and antiapoptosis." (PMID 41497797, 2025). "As the downstream transcriptional factor of the Hh pathway, GLI1 plays a crucial role in cancer progression and prognosis evaluation." (PMID 41323789, 2025). "Aberrant activation of the SHH pathway leads to the nuclear entry of the transcription factor GLI-1, where it binds to the promoter site of target genes, thereby enhancing the biological behaviors of cancer cells." (PMID 38730691, 2024). "Inhibition of DYRK1B reduces GLI1 expression, offering a potential therapeutic target for GLI1-dependent cancers resistant to SMO inhibitors." (PMID 39568072, 2024). "Initial analysis across cancer types showed that GLI1 expression is downregulated in some (e.g., BLCA, BRCA) but upregulated in others (e.g., CHOL, KIRC), compared to normal tissues." (PMID 39483334, 2024). "Our results revealed that the expression levels of GLI1/2/3 were positively correlated in most cancer tissues, suggesting a cooperative role of these factors in tumorigenesis." (PMID 38498906, 2024). "Previous studies, including the present study, have demonstrated the essential role of the Hedgehog cascade, particularly its executor GLI1, in cancer stem cell-mediated NSCLC development and progression." (PMID 37950038, 2024). "The transcription factor GLI1 is considered the main downstream effector of the Hh signaling and plays a relevant role in several cancers." (PMID 39695131, 2024). "Univariate Cox analysis for overall survival (OS) demonstrated that GLI1, GLI2, and GLI3 were risk factors for patients with 12, 8, and 6 types of cancer, respectively." (PMID 38498906, 2024). "The differential expression of GLI1 in diverse cancers underscores its significance and potential as a therapeutic target." (PMID 39483334, 2024). "In summary, our findings in pan-cancer studies suggest that GLI1/2/3 primarily play a pro-cancer role." (PMID 38498906, 2024). "The increased expression of GLI1 in various cancers is an oncogenic biomarker and a significant therapeutic target for the treatment of multiple cancers." (PMID 39769147, 2024). "By integrating single-cell datasets, we analyzed the correlation between the gene set of GLI1/2/3 and cancer-related functional states, and found that there was a correlation between the gene set of GLI1/2/3 and different cancers and functional states." (PMID 38498906, 2024). "As SUFU negatively regulates the hedgehog pathway, targeting the abnormal activity of SUFU holds promise as a therapeutic strategy to impact GLI1, a pivotal contributor to the advancement of multiple cancer types via the hedgehog signaling pathway." (PMID 39059063, 2024). "The findings reveal dysregulated expression of GLI1 in numerous cancers, with a significant decrease observed in BRCA." (PMID 39483334, 2024).
cancer (continued). "As a transcriptional activator of the Hedgehog signaling target genes, GLI1 notably translocates into the nucleus and initiates the transcription of target genes related to cancer progression." (PMID 39022130, 2024). "Specifically, the activation of the proteasome pathway highlights GLI1’s potential role in regulating protein homeostasis, which is crucial for maintaining cellular functions and processes that drive cancer progression." (PMID 39483334, 2024). "Overexpression of SMURFs, reducing GLI1 levels, induces Hh pathway downregulation and has a significant effect on Hh-driven cell proliferation and in particular in Hh-dependent cancer cells proliferation." (PMID 39695131, 2024). "Although the Hedgehog signaling pathways, including GLI1, are promising targets for cancer treatment, drug discovery efforts directly targeting GLI1 are relatively limited." (PMID 39769147, 2024). "The accumulation of Gli1 in pancreatic stellate cells (PSCs), which are crucial stromal cells in the pancreatic cancer microenvironment, can restrict access to cancer cell migration." (PMID 39062453, 2024). "Among the 33 cancer types studied, GLI1 exhibited lower expression in female tumors, including BRCA, CESC, and UCEC." (PMID 39483334, 2024). "Next, we investigated the ability of HPP-9 to degrade BET bromodomains in cancer cell lines, and its effect on GLI1 as a readout of Hedgehog pathway state." (PMID 37393376, 2023). "Accordingly, targeting the Hh/Gli1 pathway is expected to be a promising strategy for cancer therapy." (PMID 38097536, 2023). "RNA-seq analysis of the effects of 24 h exposure of QN-302 on MIA PaCa-2 cells have previously shown that the mRNA levels in the prominent cancer pathway quadruplex-containing genes such as GLI1, MAPK11 and BCL-2 were downregulated by 1–2 fold." (PMID 36985425, 2023). "The natural compound Glabrescione B also interferes with the interaction of GLI1/DNA and has shown therapeutic efficacy in preclinical models of HH-dependent cancers." (PMID 36674836, 2023). "In summary, these results showed that UHRF1 silencing reduced cancer cell stemness by suppressing GLI1 expression." (PMID 37380646, 2023). "Considering the significance of the Shh–GLI1 pathway in cancer, various therapeutic approaches have been developed over the years to block this pathway." (PMID 37894854, 2023). "The present results prove the potential suitability of small-size AgNPs in anti-cancer therapy, especially in the case of the recently proved Gli1 overexpression in GB cells." (PMID 37407723, 2023). "Recognizing the pivotal role of the Shh–GLI1 pathway in cancer, therapeutic strategies aimed at blocking this pathway have been developed over the years." (PMID 37894854, 2023). "As a result, inhibitors of the Shh–GLI1 pathway, such as cyclopamine, have been effectively tested in several cancer types, including medulloblastoma, small-cell lung cancer (SCLC), pancreatic adenocarcinoma, gastric adenocarcinomas, and esophageal cancer." (PMID 37894854, 2023). "GLI1 is expressed at low levels in differentiated tissues, and aberrant activation of GLI1 plays a role in the promotion of cancer through regulation of cell proliferation, survival, metastasis, and generation of cancer stem cells." (PMID 38062202, 2023). "The SHH pathway and its key transcription factor GLI1 play an essential role in cancer stemness-mediated tumorigenesis and multiple drug resistance in various cancers." (PMID 37149646, 2023). "Nonetheless, given the discrepancies presented in the studies, more research is needed to establish the role of GLI1 in KIRC as well as other types of cancer." (PMID 37964226, 2023). "Control and early (TNM 1 + 2) stages of KIRC revealed moderate and strong GLI1 IHC reaction, however, its intensity decreased in more advanced cancer samples (TNM 3 + 4)." (PMID 37964226, 2023). "The whole-exome sequencing of osimertinib-resistant patient-derived cancer cell lines revealed amplification of GLI1, CDK4, and CCND1." (PMID 35584089, 2022).